PDK2 (pyruvate dehydrogenase kinase 2)
Diseases named in the same sentence as PDK2 in open-access papers (continued):
Sharing a sentence is not in itself a finding about the gene and the disease.
Obesity (5 papers, 2019 to 2023). Accumulation of substantial excess body fat. "Mice with global or adipose tissue-specific PDK2 deficiency were protected against diet-induced obesity." (PMID 34552205, 2021). "Mice deficient in PDK2 were protected from diet-induced obesity, and PDK 1 and 2 activity was increased during the generation of fat cells." (PMID 34552205, 2021). "It is proposed that the metabolic effects of PDK2 deficiency reduce obesity by limiting full differentiation of preadipocytes into adipocytes, which in turn limits adipocyte hypertrophy." (PMID 34552205, 2021). "Transplantation of PDK2/4-deficient bone marrow into irradiated wild-type mice to produce mice with PDK2/4-deficient myeloid cells prevented M1 polarization, reduced obesity-associated insulin resistance, and ameliorated adipose tissue inflammation." (PMID 31134063, 2019). "In this cohort, a positive correlation between the PDK1/2 and PPARγ expression levels was noted, suggesting that like PPARγ expression, PDK1 and PDK2 expression might be implicated in the pathogenesis of human obesity." (PMID 34552205, 2021). "We also used an HFD-induced obesity and type 2 diabetes mouse model to assess calorie intake, blood glucose level, body size, cold-induced thermogenesis capacity, and food intake-related neuropeptide expression in WT and Pdk2 KO mice." (PMID 33219201, 2020). "Increased expression of PDK1 and PDK2 by JUN and FOS enforces HIF1a stability to facilitate adipocyte differentiation and obesity." (PMID 34552205, 2021).
ovarian carcinoma (5 papers, 2016 to 2025). A malignant neoplasm originating from the surface ovarian epithelium. "Indicating that the phosphorylation site of FOXK2 regulated by PDK2 sustained glycolysis in ovarian cancer." (PMID 38734828, 2024). "High levels of PDK2 have been identified in chemoresistant ovarian cancer tissues and cell lines, correlating with shorter progression-free survival." (PMID 39479443, 2024). "Additionally, FOXK2 transcriptionally regulates the expression of PDK2, thereby creating a positive feedback loop that sustains glycolysis in ovarian cancer cells." (PMID 40641601, 2025). "A novel approach involves the use of FSH receptor-mediated nanocarriers for in vivo delivery of PDK2 shRNA, leveraging the FSH receptor's specific expression in ovaries as a targeting site for ovarian cancer." (PMID 39479443, 2024). "In ovarian cancer, the expression of PDK1 and PDK4 were relatively low compared to PDK2, so we haven’t further explored whether they can phosphorylate FOXK2." (PMID 38734828, 2024). "As expected, concurrent over-expression of PDK2 and PDK1 enhanced the phosphorylation of PDHE1α, abolished the sensitizing function of DCA and partially abrogated the lethal effect of DCA plus Met in ovarian cancer cells." (PMID 27449090, 2016).
colorectal cancer (4 papers, 2020 to 2024). A primary or metastatic malignant neoplasm that affects the colon or rectum. "Our findings reveal that the OGT–c-Myc–PDK2 axis plays a key role in regulating glucose metabolism in colorectal cancer, and suggest new therapeutic strategies." (PMID 38778217, 2024). "Together, these results indicated that c-Myc impacts colorectal cancer cell proliferation and tumor growth via regulating PDK2." (PMID 38778217, 2024). "Blocking Ser415 O-GlcNAcylation on c-Myc suppressed PDK2 expression, enhanced ROS levels, and decreased colorectal cancer cell proliferation and tumor growth in nude mice." (PMID 38778217, 2024). "Kaplan-Meier analysis in TCGA database revealed that PDK2 mRNA expression levels were positively correlated with poor survival of patients with colorectal cancer." (PMID 38778217, 2024). "This study highlights the OGT–c-Myc–PDK2 axis as a key mechanism linking oncoprotein activation with deregulated glucose metabolism in colorectal cancer." (PMID 38778217, 2024). "Collectively, these results support the cellular data, and underscore the importance of the OGT–c-Myc–PDK2 axis in colorectal cancer development." (PMID 38778217, 2024). "Thus, our study identifies OGT–c-Myc–PDK2 axis as a key mechanism to regulate colorectal cancer metabolism." (PMID 38778217, 2024).
Hepatic steatosis (4 papers, 2019 to 2025). Steatosis is a term used to denote lipid accumulation within hepatocytes. "As an important regulator of glucose metabolism, PDK2 is associated with many diseases, such as tumor metabolic reprogramming, hepatic steatosis, and type 2 diabetes, and is closely correlated with immune cell dysregulation and inflammatory responses." (PMID 38193078, 2023). "Mice with high-fat-diet-induced hepatic steatosis demonstrated benefits from having enhanced PDH activity from inhibition of pyruvate dehydrogenase kinase 2 and decreased PC flux through increased fatty acid oxidation and ketone body formation." (PMID 39940422, 2025). "The involvement of PDK2 in hepatic steatosis and cancer, via the regulation of glucose metabolism pathways, has been reported, and the upregulation of PDK2 expression in tumor cells is usually considered an important driver of metabolic rewiring." (PMID 38193078, 2023). "Inhibition of PDK2 prevents hepatic steatosis induced by a high-fat diet in mice." (PMID 39621302, 2024).
Hyperglycemia (4 papers, 2013 to 2024). An increased concentration of glucose in the blood. "To study whether hyperglycemia can cause inflammatory activation of astrocytes and to assess the role of PDK2 in this condition, we compared glucose responses of astrocytes isolated from WT and Pdk2 KO early postnatal mouse brain tissues." (PMID 33219201, 2020). "A hyperglycemia-induced increase in the expression of PDK2 and phosphorylation of PDH leads to a glycolytic shift in the diabetic hypothalamus." (PMID 33219201, 2020). "Metabolic analyses reveal that deletion of the Pdk4 gene had better improvement in hyperglycemia and glucose tolerance than knockout of the Pdk2 gene whereas the Pdk2 gene deletion showed better insulin tolerance as compared to the Pdk4 gene inactivation on the Irs1/2 knockout genetic background." (PMID 23940800, 2013). "Besides, hyperglycemia has been recently shown to induce an increase expression of pro-inflammatory lipocalin-2 (LCN2) in DRG SGCs, potentiating neuroinflammation and neurotoxicity via LCN2-pyruvate dehydrogenase kinase isoform 2 (PDK2)-lactic acid pathway contributing to the progression of DPN." (PMID 38236305, 2024).
Insulin resistance (4 papers, 2013 to 2025). Increased resistance towards insulin, that is, diminished effectiveness of insulin in reducing blood glucose levels. "To examine whether Pdk2 or Pdk4 knockout might affect insulin resistance in IrsLDKO mice, we performed insulin tolerance tests." (PMID 23940800, 2013). "Of importance is that deletion of both PDK2 and PDK4 is associated with reduced weight gain, insulin resistance, and adipose tissue inflammation, emphasizing the promising effect of targeting macrophage glucose oxidation in mitigating insulin resistance and tissue inflammation in obesity." (PMID 39198360, 2025). "Insulin tolerance tests did not reveal a significant improvement in either Pdk2 or Pdk4 knockdown mice although Pdk4 knockdown had a trend of improvement of insulin resistance." (PMID 23940800, 2013).
autosomal dominant polycystic kidney disease (3 papers, 2009 to 2025). Autosomal dominant form of polycystic kidney disease. "The PDK-2 gene, encoding PC-2, is mutated in patients with autosomal dominant polycystic kidney disease." (PMID 19435523, 2009).
lung adenocarcinoma (3 papers, 2021 to 2022). A carcinoma that arises from the lung and is characterized by the presence of malignant glandular epithelial cells. "PDK2 transcriptionally regulated CNNM3 expression in lung adenocarcinoma and conferred the cisplatin resistance." (PMID 36474273, 2022). "Other arrhythmic genes, such as PDK2, have prognostic abilities in lung adenocarcinoma." (PMID 35832846, 2022).
chronic periodontitis (2 papers, 2022 to 2024). A chronic inflammatory process that affects the tissues that surround and support the teeth. "Additionally, Lower PDK2 protein levels were associated with chronic periodontitis, and PDK2 modulates metabolic and inflammatory processes in the hypothalamus." (PMID 38376420, 2024).
colitis (2 papers, 2024 to 2025). Inflammation of the colon. "PDK4 deletion in CD4+ T cells attenuates colitis through metabolic regulation, underscoring the need for comprehensive investigation of PDK2’s immunometabolic role in IBD." (PMID 40821793, 2025). "And the results also demonstrated that CD86 exhibited higher expression in mouse colitis lesions, whereas PDK2, CHDH, and ALDH5A1 displayed lower expression in these lesions." (PMID 38376420, 2024). "Western blotting analysis demonstrated a reduction in the protein expression levels of ALDH5A1, PDK2, and CHDH in the colitis lesions of mice administered with DSS." (PMID 38376420, 2024). "Ultimately, the verification of the expression of signature genes (ALDH5A1, CHDH, and PDK2) and their co-expression with M1 macrophages (CD86) was accomplished through the construction of inflammatory cell and colitis models." (PMID 38376420, 2024). "Collectively, our findings indicate that the influence of PDK2, CHDH, and ALDH5A1 on the advancement of DSS-induced colitis in mice is potentially mediated through the regulation of macrophage infiltration." (PMID 38376420, 2024). "The results demonstrated a downregulation of mRNA and protein expression levels of PDK2, CHDH, and ALDH5A1 in colitis cells and tissues, which aligns with our previous bioinformatic analysis." (PMID 38376420, 2024). "Additionally, the expression levels of PDK2, CHDH, and ALDH5A1 were lower in colitis tissues, which aligns with the results obtained from the bioinformatic analysis." (PMID 38376420, 2024).
dyslipidemia (2 papers, 2020 to 2024). "Ang II did not alter the relative expression of several enzymes in lipid metabolism; however, the expression of pyruvate dehydrogenase kinase 2 (PDK2) was increased, and PDK2 can be protective against dyslipidemia." (PMID 39199363, 2024). "Here, we report the first evidence linking PDK2 with RAS, mitochondrial dysfunction, and dyslipidemia in rat colonocytes, and further studies are warranted to investigate direct causation." (PMID 39199363, 2024).
glioma (2 papers, 2022). A benign or malignant brain and spinal cord tumor that arises from glial cells (astrocytes, oligodendrocytes, ependymal cells). "Under short‐term treatment conditions compared to vehicle‐treated control cells, glioma cells exhibited minimal or no change in PDK1, PDK2, PDK3, and PDK4 protein expression." (PMID 34058053, 2022).
gout (2 papers, 2020 to 2022). A condition characterized by painful swelling of the joints, which is caused by deposition of urate crystals. "A transcript assay revealed that PDK2 and ABCG2 gene expression levels are positively correlated; thus, the regulators of PDK2 interact with ABCG2 to indirectly influence gout incidence." (PMID 35813212, 2022). "Through this strategy, our results suggested that epistatic interactions between PDK2 and ABCG2 contributed to serum urate and gout and that PKD2 is supposed to influence the progression from elevated serum urate to hyperuricemia to gout by epistatically interacting with ABCG2." (PMID 32000861, 2020).
Hypoglycemia (2 papers, 2019). A decreased concentration of glucose in the blood. "As a result of PDK2 immunostaining, we found that the level of PDK2 significantly increased in the hypoglycemia-induced group compared to the sham group." (PMID 31052436, 2019). "Thus, we found that DCA reduced microglia and astrocyte activation by inhibiting PDK2 in the hippocampal CA1 region after hypoglycemia." (PMID 31052436, 2019). "Similarly, Jeoung et. al. showed that inactivation of PDK2/4 in mice resulted in hypoglycemia and ketoacidosis." (PMID 31712597, 2019). "It is unclear exactly how PDK2 is increased by hypoglycemia/glucose reperfusion." (PMID 31052436, 2019).
myocardial infarction (2 papers, 2015 to 2025). Gross necrosis of the myocardium, as a result of interruption of the blood supply to the area, as in coronary thrombosis. "An increased mRNA expression of Irs-1, Prkcz (a downstream of IRS-1 and PI3K), pyruvate dehydrogenase kinase (Pdk)-1, and Pdk-2 was observed in diabetic rats after myocardial infarction." (PMID 26229969, 2015).
osteoporosis (2 papers, 2020 to 2024). A condition of reduced bone mass, with decreased cortical thickness and a decrease in the number and size of the trabeculae of cancellous bone (but normal chemical composition), resulting in increased fracture incidence. "Future endeavors will encompass the verification of Circ_HECW2's regulatory mechanism in vivo, coupled with a more in-depth analysis of PDK2, to advance our understanding of the comprehensive regulatory landscape in osteoporosis." (PMID 38183099, 2024). "In summary, our findings underscore the diagnostic significance the heightened expression of Circ_HECW2 in osteoporosis (OP), shedding light on its role in fostering osteoclast apoptosis through the intricate miR-1224-5p/PDK2 axis." (PMID 38183099, 2024). "Ovariectomy, a procedure that induces estrogen-dependent osteoporosis, of Pdk2 null (Pdk2−/−) mice show reduced osteoclast number, suppressed osteoclastogenesis, and suppressed bone resorption through the RANKL‒CREB‒c-Fos‒NFATc1 pathway." (PMID 33256181, 2020).
ovarian clear cell cancer (2 papers, 2024). An invasive malignant neoplasm that arises from the ovary and is characterized by a predominance of clear and hobnail malignant epithelial cells. "PDK2 leads to cisplatin resistance in ovarian clear cell carcinoma through suppression of mitochondrial function." (PMID 38734828, 2024).
prostate carcinoma (2 papers, 2022 to 2023). A carcinoma that arises from epithelial cells of the prostate gland. "Correlation between clinical and pathological variables and PDK1, PDK2, PDK3 and PDK4 protein expression in prostate cancer." (PMID 35692804, 2022).
Sepsis (2 papers, 2021 to 2025). Sepsis is defined as life-threatening organ dysfunction caused by a dysregulated host response to infection. "We assumed that another three cis-eQTL genes (PDK2, RPS18, and NDUFV3), which were negatively associated with sepsis-induced ARDS, could be targeted with potential drugs in ARDS treatment." (PMID 40116326, 2025). "Subsequent drug target analysis confirmed the role of four targets (PSMA4, PDK2, RPS18, and NDUFV3) as druggable genes for sepsis-related ARDS." (PMID 40116326, 2025). "We discovered potential drug targets for sepsis-related ARDS through a comprehensive analysis, among which four druggable targets (PSMA4, PDK2, RPS18, and NDUFV3) should be dialectically treated." (PMID 40116326, 2025).
type 2 diabetes (2 papers, 2017 to 2020). "In type 2 diabetes, the two isoforms PDK2 and PDK4 are induced in a tissue-specific manner." (PMID 28298922, 2017). "In type 2 diabetes, decreased levels of insulin promote an increase in both PDK4 gene expression and PDK2 mRNA levels." (PMID 28298922, 2017).
brain injuries (1 paper, 2022). "It has been reported that determine pyruvate dehydrogenase (PDH) is important for the changes in brain energy metabolism seen in various brain injuries, and DCA, a structural analogue of pyruvate, is attached to the pyruvate binding site to inhibit PDK in the order of PDK2 > PDK1, PDK4 > PDK3." (PMID 36432491, 2022).
chronic hepatitis B (1 paper, 2024). "Consistent with our in vitro findings, in people with chronic hepatitis B there was significantly increased expression of PDK1, PDK2, and PDK3 compared to healthy liver, with a strong trend towards increased expression of LDHA (P =0.057)." (PMID 38655824, 2024).
Co-infection (1 paper, 2025). "The marked 35.5-fold upregulation of PDK2 likely reflects cortisol-induced stress in response to co-infection." (PMID 40943072, 2025).
colon carcinoma (1 paper, 2021). "The replacement of miR-149, normally suppressed by SNAIL2 in colon carcinoma, was associated with an inhibition of EMT and 5-FU chemo-resistance upon the targeting of MYC and nanog homeobox (NANOG) and with a reduction in glucose metabolism after pyruvate dehydrogenase kinase 2 (PDK2) inhibition." (PMID 34503164, 2021).
colorectal tumor (1 paper, 2024). "Furthermore, c-Myc S415 glycosylation levels positively correlate with PDK2 expression levels in clinical colorectal tumor tissues." (PMID 38778217, 2024).
glioblastoma (1 paper, 2014). The most malignant astrocytic tumor (WHO grade IV). "Brain aging is associated with reduced PDK1 and PDK2 mRNA in the cerebellum and elevated PDK2 mRNA in the hippocampus and cerebral cortex, and PDK2 mRNA up-regulation was involved in glioblastoma." (PMID 24520982, 2014).
heart failure (1 paper, 2019). Inability of the heart to pump blood at an adequate rate to meet tissue metabolic requirements. "The protein expression levels of PDK1 and PDK2 were unaffected by heart failure." (PMID 30881593, 2019). "PDK3 expression was not measured due to low expression in the heart, whereas mRNA expression changes in PDK2 and PDK4 isoforms have been reported for human heart failure." (PMID 30881593, 2019).
hyperlipidemia (1 paper, 2024). "In contrast, these effects are ameliorated in mice that are deficient in PDK2 globally or in adipose-specific tissues, suggesting a role for PDK2 in hyperlipidemia." (PMID 39199363, 2024).
ischemic stroke (1 paper, 2025). A stroke disorder caused by obstruction of blood flow to the brain, due to thrombotic (local blood clot formation) or embolic (due to a blood clot or other material traveling from another site) event. "Meanwhile, our results reveal that silencing PDK2 can significantly inhibit the release of ROS, which further highlights the pivotal role of PDK2 in the treatment of ischemic stroke." (PMID 40756350, 2025).
lentivirus infection (1 paper, 2018). Virus diseases caused by the Lentivirus genus. "To determine the impacts of PDK2 on GC cells, we elevated PDK2 expression in MGC803 and HGC27 cells, and repressed its expression in SGC7901 and BGC823 cells by lentivirus infection and verified the altered expression of PDK2 in these GC cell lines by western blotting." (PMID 29725130, 2018).
liver cancer (1 paper, 2022). An epithelial or non-epithelial malignant neoplasm that arises from the liver. "In our current study, we further confirmed that as the target gene of miR-124 or miR-506, PDK2 can also be involved in the prevention of miR-124- or miR-506-mediated liver cancer cell proliferation and invasion." (PMID 35212603, 2022).
male infertility (1 paper, 2025). The inability of the male to effect fertilization of an ovum after a specified period of unprotected intercourse. "Some studies have found that PDK2 dysfunction often leads to male infertility and human reproductive defects, indicating that PKD2 plays an important role in the reproductive system." (PMID 39958158, 2025).
osteosarcoma (1 paper, 2025). A usually aggressive malignant bone-forming mesenchymal neoplasm, predominantly affecting adolescents and young adults. "Given that PDK is a crucial regulator of glycolysis and oxidative phosphorylation, we hypothesized that PDK2 may influence the energy metabolism of osteosarcoma cells by modulating the balance between glycolysis and oxidative phosphorylation, thereby playing a role in the progression of OS." (PMID 40070565, 2025).